MPZL3 (myelin protein zero like 3)
Diseases named in the same sentence as MPZL3 in open-access papers (continued):
Sharing a sentence is not in itself a finding about the gene and the disease.
cancer (4 papers, 2020 to 2025). A tumor composed of atypical neoplastic, often pleomorphic cells that invade other tissues. "The MPZL3 gene is located on chromosome 11q23.3, a region known to be susceptible to chromosomal loss across multiple cancer subtypes." (PMID 40631617, 2025). "The association of MPZL3 expression with all four methyltransferases in 33 types of cancer was also evaluated." (PMID 35965540, 2022). "TMB, MSI, MMR, DNA methylation, and RNA modification played a significant role in mediating MPZL3 dysregulation in cancers, and MPZL3 was closely linked to CD8+ T cells and CD4+ T immune infiltration." (PMID 35965540, 2022). "We next analyzed the association of MPZL3 expression with immune cell infiltration and drug susceptibility in human cancers." (PMID 35965540, 2022). "The MPZL3 genetic alteration in different cancer types across protein domains was also detected, and missense mutation of MPZL3 was the main type of genetic alteration." (PMID 35965540, 2022). "This study aimed to analyze the role of myelin protein zero-like 3 (MPZL3), a single membrane glycoprotein, in prognosis, tumor immune infiltration, and drug susceptibility in human cancers." (PMID 35965540, 2022). "In general, MPZL3 expression was highly associated with four DNA methyltransferases in the majority of cancers." (PMID 35965540, 2022). "Further work is needed to establish whether MPZL3 acts directly as a CAM, as it contains an IgV domain, or if it alters adhesion indirectly in epithelial cells, and how MPZL3 loss drives an EMT phenotype in cancer cells." (PMID 40631617, 2025). "Loss of 11q23, in which the MPZL3 gene resides, is frequently observed in cancer." (PMID 40631617, 2025). "MPZL3 expression was strongly positively or negatively associated with TMB in 33 types of cancers." (PMID 35965540, 2022). "Furthermore, TMB, MSI, MMR, DNA methylation, and RNA modification play a significant role in mediating MPZL3 dysregulation in cancers, and MPZL3 is closely linked to tumor immunity and acts as a suitable target for antitumor immunity therapeutics." (PMID 35965540, 2022). "This suggests that loss of MPZL3 may be a phenotype of cancer." (PMID 40631617, 2025). "Thus, previous studies and ours all indicated that MPZL3 mRNA expression might be a reliable diagnostic factor and potentially promising biomarker for pan-cancer diagnosis." (PMID 35965540, 2022). "Previous research indicates varying MPZL3 expression patterns across different cancer types, suggesting that the role of MPZL3 is context-dependent." (PMID 40631617, 2025). "CNA analysis revealed that the MPZL3 locus, 11q23.3, is frequently altered across multiple cancer types." (PMID 40631617, 2025). "MPZL3 promotes homotypic cancer cell adhesion, and decreasing MPZL3 expression enhances invasion and clearance of mesothelial cell monolayers." (PMID 40631617, 2025). "Our data suggests that loss of MPZL3 is reminiscent of the changes in E-cadherin observed during EMT and cancer metastasis." (PMID 40631617, 2025). "Next, we applied the TIMER, MCPcounter, and CIBERSORT algorithms to further investigate the potential relationship between the infiltration level of various immune cells and MPZL3 expression in different types of cancers from the TCGA database." (PMID 35965540, 2022). "Conclusively, all of the present studies showed that MPZL3 was upregulated in pan-cancer tissues, and high MPZL3 expression was correlated with worse survival outcomes in pan-cancer." (PMID 35965540, 2022). "We found that MPZL3 expression was different in paired tumor and normal tissues of 27 cancer types based on the data from the TCGA and GTEx databases." (PMID 35965540, 2022). "Further analysis of the emerging biology of HER3 and MPZL3 and their activities in human cancer will be critical to fully exploiting their potential in cancer therapy." (PMID 35249128, 2022). "The results revealed that MPZL3 was highly related to MMR genes in 33 cancers, except for GBM and LUSC." (PMID 35965540, 2022).
cancer (continued). "In the present study, with the help of public databases such as The Cancer Genome Atlas (TCGA), we comprehensively investigated the relationship between MPZL3 expression and prognosis in different cancer types for the first time." (PMID 35965540, 2022). "MPZL3 was highly expressed in most cancer types and correlated with unfavorable survival outcomes in several cancers." (PMID 35965540, 2022). "All of this evidence implies that MPZL3 can be used as a possible oncogene and promising biomarker for the diagnosis of pan-cancer." (PMID 35965540, 2022). "Under pan-cancer analysis, we successfully identified that MPZL3 acts as a pan-cancer gene and investigated its differential expression, prognostic value, tumor immune infiltration, and drug susceptibility in human cancers." (PMID 35965540, 2022). "The Kaplan–Meier survival analysis of OS, PFI, DSS, and DFI by TCGA data identified that MPZL3 mRNA expression levels have a prognostic role across cancers." (PMID 35965540, 2022). "To investigate the role of MPZL3 in tumor immune infiltration, we integrated the ImmuneScore, StromalScore, and ESTIMATEScore across cancers with MPZL3 expression." (PMID 35965540, 2022). "Because of the potential prognostic value, biological function, and possible drug sensitivity guidance that MPZL3 brings, it is necessary for us to further explore the fundamental mechanism of MPZL3 and its dysregulation across cancers." (PMID 35965540, 2022). "Gene expression analysis of HER3-depleted cells identified MPZL3, encoding a single-pass transmembrane protein, as HER3-dependent effector in multiple MET-amplified cancer cell lines." (PMID 35249128, 2022). "The CIBERSORT algorithm also indicated that MPZL3 mRNA expression exhibited varying degrees of immune infiltration signatures in different types of cancers." (PMID 35965540, 2022). "MPZL3 (Myelin protein zero like 3) is involved in mediating cell adhesion but little is known about its possible role in cancer pathways." (PMID 32341500, 2020). "Thus, the CCLE copy number and gene expression data support the elevation of MPZL3 mRNA levels downstream of multiple amplified RTKs in human cancer-derived cell lines." (PMID 35249128, 2022). "Furthermore, we conducted co-expression analyses to analyze the correlations of MPZL3 expression with HALLMARKS enrichment scores in 33 cancer types." (PMID 35965540, 2022). "Additionally, the Kaplan-Meier analysis results indicated that MPZL3 mRNA expression is significantly related to prognosis in cancers, especially patients with GBM, BRCA, LGG, and PAAD." (PMID 35965540, 2022). "In addition, a significant positive correlation was observed between the association of CD8+ T cells and CD4+T immune infiltrations with MPZL3 expression in most types of cancers based on MCPcounter algorithms." (PMID 35965540, 2022). "We further investigated the possible roles of MPZL3 in the stemness of cancers." (PMID 35965540, 2022). "All of these results implied that MPZL3 expression actively participates in various biological processes and that different levels of MPZL3 mRNA exert different biological functions in different types of cancers." (PMID 35965540, 2022). "Moreover, MPZL3 contains an Ig-like domain, which may be involved in mediating interactions between cancer cells and immune cells." (PMID 40631617, 2025). "Notably, the majority of MPZL3 expression positively correlated with DNAss and RNAss in the 33 TCGA cancers, which suggested that high MPZL3 expression predicted a high index of the tumor stemness score (DNAss and RNAss), strong activity of tumor stem cells and a low degree of tumor differentiation." (PMID 35965540, 2022). "Therefore, we speculated that MPZL3 expression exerted different biological functions in different types of cancers." (PMID 35965540, 2022). "Thus, the data demonstrated that MPZL3 is abnormally expressed in different cancers." (PMID 35965540, 2022).
cancer (continued). "However, the role of MPZL3 in cancer progression and its regulation remains poorly defined." (PMID 35249128, 2022). "Together, these observations support a role for MPZL3 for proliferation in MET-amplified cells, and that HER3-dependent MPZL3 levels may underlie a requirement for HER3 for robust proliferation in MET-amplified cancers." (PMID 35249128, 2022). "While we have observed a role for MPZL3 in a HER3-dependent proliferative response in MET-amplified cells, it is unclear whether this is a specific requirement of Met-dependent transformation independent of HER3 or whether MPZL3 expression is associated with RTK amplification in cancer." (PMID 35249128, 2022). "We analyzed the correlation of MPZL3 expression with OS, PFI, DSS and DFI in type of cancers, and the results are displayed in forest charts." (PMID 35965540, 2022). "As MPZL3 and HER3 interact directly, it may be possible to identify cancers dependent on this interaction and the upstream activity of HER3-activating kinases, such as Met, EGFR and HER2, via this mechanism." (PMID 35249128, 2022). "To investigate the potential prognostic value of MPZL3 in cancers, we integrated the MPZL3 mRNA expression level with the overall survival (OS), progression-free interval (PFI), disease-specific survival (DSS) and disease-free survival (DFI) of the 33 cancer types in the TCGA database." (PMID 35965540, 2022). "To understand if MPZL3 expression co-occurs in cancers with amplified RTKs, we interrogated the Cancer Cell Line Encyclopedia (CCLE) genomic copy number and gene expression data to explore the relationship between RTK amplification and MPZL3 expression (copy relative to ploidy + 1 ≥ 2.3)." (PMID 35249128, 2022). "However, the specific roles and mechanisms of MPZL3 in the TME, particularly in tumor immune infiltration in cancer, have not yet been studied." (PMID 40631617, 2025).
tumor (4 papers, 2020 to 2025). "CNA analysis of International Cancer Genome Consortium/TCGA PanCaner Atlas data across 24 tumor types found that many tumor samples exhibit MPZL3 copy-number loss." (PMID 40631617, 2025). "We further assessed the mutation frequency and mutation count, including mutation, amplification, and deep deletion of MPZL3, in different tumor samples by the cBioPortal database." (PMID 35965540, 2022). "Tumor-associated signaling pathways, immune regulation, cell cycle, apoptosis, chemokine-related pathways, chemokine receptor proteins, etc., are closely associated with MPZL3 expression." (PMID 35965540, 2022). "Thus, it is possible that a loss of MPZL3 could also influence the recruitment of tumor-associated immune cells." (PMID 40631617, 2025). "However, the roles and underlying mechanisms of MPZL3 in prognostic value, tumor immune infiltration, and drug susceptibility largely remain unclear." (PMID 35965540, 2022). "The analyzed genes encoded tumor-associated signaling pathways, immune regulation, cell cycle, apoptosis, chemokine-related pathways, chemokine receptor proteins, etc., and the heatmap indicated that these hallmarks are closely associated with MPZL3 expression." (PMID 35965540, 2022). "This was somewhat surprising as senescence is generally associated with increased DNA damage, yet we conversely observed decreased DNA damage in response to MPZL3 knockdown in OVCAR4 tumor tissues and in cell culture in response to these compounds." (PMID 40631617, 2025). "To further assess the expression of MPZL3 during tumor progression, we compared MPZL3 transcript expression in ovarian and omental tumors to matched normal fallopian tube specimens from an independent tissue bank at the University of Pittsburgh." (PMID 40631617, 2025). "All of these results indicated that MPZL3 played a significant role in tumor immunity regulation." (PMID 35965540, 2022). "Yet the role and consequences of altered MPZL3 expression have not been explored in tumor development and progression." (PMID 40631617, 2025). "Moreover, the effects of MPZL3 loss on OVCAR4 chemosensitivity were less striking in vivo, and this is likely attributable to additional factors, including interactions with the tumor microenvironment, that are absent in vitro." (PMID 40631617, 2025). "Whether MPZL3 has similar properties in tumor cells has not been explored." (PMID 40631617, 2025).
MPZL3 also shares sentences with these, for which no sentence is quoted: autoimmune (1 paper); hereditary hypotrichosis simplex (1); infection (1); Insulin resistance (1); ovarian adenocarcinoma (1); type 2 diabetes mellitus (1).